MMP2 (matrix metallopeptidase 2)
Diseases named in the same sentence as MMP2 in open-access papers (continued):
Sharing a sentence is not in itself a finding about the gene and the disease.
cancer (continued). "This is the first study that identifies a new Rab40b–Tks5- and miR-204-dependent invadopodia transport pathway that regulates MMP2 and MMP9 secretion, and extracellular matrix remodeling during cancer progression." (PMID 27789576, 2016). "The overexpression of these microRNAs were associated to an oncogenic activity in pancreatic cancer by promoting the expression of MMP-2 and MMP-9, consequently inducing cancer cell invasion, through the down-regulation of TIMP-2." (PMID 27187371, 2016). "Previous studies have revealed that inhibiting the activity of MMP-2 and MMP-9 reduces cancer cell metastasis." (PMID 26980735, 2016). "Overexpression of MMP1, MMP2, MMP3, MMP7, MMP9, and MMP13 correlates with worse outcomes in cancer patients." (PMID 27908290, 2016). "Upregulations of MMP2, MMP7, and MMP9 have been mostly reported as enhancements to the migratory and invasive ability of cancer cells." (PMID 26701209, 2016). "Overall, honey constituents are shown to lower the expression of MMP-2 and MMP-9 in a range of cancer cell lines, however, currently there is limited evidence on the effect of honey on the metastatic properties of cancer." (PMID 28933410, 2016). "As type IV collagen is the major component of the basement membrane, MMP-2 and MMP-9 have crucial roles in the early stages of cancer invasion and metastasis." (PMID 27618887, 2016). "Extracellular matrix-degrading MMPs, especially MMP-2 and MMP-9, are involved in the metastasis of cancer cells." (PMID 27733866, 2016). "Previous studies have shown that MMP-2 and MMP-9 play a critical role in cancer cell invasion by stimulating the degradation of the ECM31." (PMID 27251589, 2016). "The review performed by Abba M and colleagues, comprising data from 55 different studies, showed a group of 13 miRNAs that target the matrix metalloproteinases (MMPs) MMP-2 and MMP-9 in a large variety of cancers types." (PMID 27187371, 2016). "The role of MMP-2 and MMP-9 in metastasis is to degrade proteins in the extracellular matrix, and eventually affect cancer progression and invasion." (PMID 27618887, 2016). "In prostate cancer, CAFs have been shown to affect the proliferation and facilitate the invasiveness of cancer cells by CXCL12, CXCL14, MMP2 and MMP3." (PMID 26954362, 2016). "The levels of endothelial cell marker VE-cadherin, matrix metalloproteinase (MMP)-2 and MMP-9 expression were measured in CD133+ cancer stem cells and xenograft tumors in nude mice injected with CD133+ and CD133– cells, respectively." (PMID 27074560, 2016). "MMP-2 and MMP-9 are important members of soluble MMPs and play important roles in cancer development." (PMID 27618887, 2016). "Previous studies in human cancers revealed an unrecognized interplay between Angiogenin (ANG) and matrix metalloproteinase-2 (MMP2) leading to pronounced tumorigenesis." (PMID 27317771, 2016). "For resveratrol, studies have demonstrated its anti-metastatic effect against several types of cancers by downregulation of MMP expression and its enzymatic activities, mainly MMP-2 and MMP-9." (PMID 27834913, 2016). "Elevated endogenous WNT11 increases activity of MMP2 and MMP9, and promotes proliferation, migration and invasion of cancer-derived cells." (PMID 26861754, 2016). "Compared with these two cancer cell lines, OSE and OVCA433 cells maintained high levels of MMP2 and ZEB1 in both Matrigel and collagen 3D cultures." (PMID 26684027, 2016). "MMP1 and MMP14 have been reported to induce cancer cell invasion, and MMP14 is further recognized in the activation of MMP2 and MMP9." (PMID 26981862, 2016). "A number of previous studies showed an increase in the expressions of MMP-2 and MMP-9 within various malignancies, and these enzymes were proposed as potential cancer markers." (PMID 27406386, 2016). "MMP14 has been shown to play a critical role in cancer invasion by inducing ECM degradation and increasing the secretion of other MMPs such as pro-MMP2." (PMID 27564100, 2016).
cancer (continued). "ERK-induced MMP-2 and MMP-9 have been reported to degrade extracellular matrix, provoking cancer cell invasion into stroma; therefore, we used gelatin zymography to evaluate MMP-2 and MMP-9 activities at different miR-550a-5p concentrations." (PMID 27462780, 2016). "Silencing of TM4SF1 also increases the expression of TIMP (an inhibitor of MMP), inhibits the expression of pro-angiogenic genes (uPA, MMP-2, MMP-9, and VEGF) and suppresses the proliferation, invasion and metastasis of cancer cells." (PMID 27153056, 2016). "The levels of endothelial cell marker VE-cadherin, MMP-2 and MMP-9 expression in CD133+ cancer stem-like cells and xenograft tumors of nude mice injected with CD133+ cells were significantly higher than those with CD133− cells." (PMID 27074560, 2016). "In tissue culture and in the liver colonies derived from cancer cells with knockdown of S100A8 and S100A9, MMP2 and MMP9 expression was decreased, consistent with the reduction in migration and invasion." (PMID 27086923, 2016). "In this regard, oncogenic RAS-mediated upregulation of MMP2, MMP9, and cathepsin B has been shown to be particularly important in stimulating cancer cell proteolytic activity and invasion." (PMID 27351226, 2016). "BITC suppressed apoptosis and cancer cells metastasis by activating caspase-3 activity and restraining CXCR4 and MMP2/9 expression." (PMID 27716619, 2016). "Emerging evidences have suggested that Notch1 induces increase of MMP-2 and MMP-9 expression that were important in cancer invasion and the extracellular matrix remolding during VM development." (PMID 27793002, 2016). "Therefore, the sustained promotion of cancer cell invasion by irradiated macrophages may be associated with the fact that MMP-2 and MMP-9 activity is not being affected by radiation exposure." (PMID 26735768, 2016). "Whereas all of the assessed genes showed high expression in fibroblasts, several genes, including SPARC, ADAM12, TIMP2, MMP2, and COL5A2 were also expressed in carcinoma cells, albeit at lower levels." (PMID 27128408, 2016). "Quantitative reverse transcription–PCR of MMP-2 and VEGF in cancer cells demonstrates that MMP-2 and VEGF mRNA was down-regulated expression." (PMID 26299580, 2015). "While HIF-1α is known to regulate proteolytic enzymes such as uPAR, cathepsins, MMP-1, MMP-2, MMP-9 in many cancer types, HIF-2α has directly been involved in membrane bound MT1-MMP in von Hippel-Lindau renal cell carcinoma." (PMID 26305551, 2015). "Since MMP2 and MMP9, which were suggested to play essential functions on ECM degradation and promote invasiveness of cancer cells, the expressions and activities of MMP2 and MMP9 were determined by qRT-PCR and ELISA assay." (PMID 26177288, 2015). "We have shown that IWR-1 significantly reduces the MMP2 and MMP9 activities in the cancer cells, even in the presence of TNF-α-induced cancer cell stimulation." (PMID 26450645, 2015). "Matrix metalloproteinase-2 (MMP-2) and −9 (MMP-9) are deeply involved in the pathogenesis of CVDs and cancers." (PMID 26637202, 2015). "It was shown that although TNF-α increased gelatin degradation by MMP2 and MMP9 in HCT116 cell supernatants, IWR-1significantly reduced the MMP2 and MMP9 activities in the cancer cells, even in the presence of TNF-α-induced cancer cell stimulation." (PMID 26450645, 2015). "It is reported that activation of both PI3K/Akt and ERK/MAPK pathways increases MMP2 and decreases TIMP1 expression in cancer cells." (PMID 25909166, 2015). "Among MMPs, MMP2 and MMP9 were found to be overexpressed and mediated higher rates of invasion and metastasis in various types of cancers." (PMID 26084564, 2015). "MMP14, MMP2, and MMP9 have all been shown to be important in cancer progression and enriched at the invadopodia." (PMID 25699257, 2015). "Elevated levels of MMP-2 and MMP-9 are often correlated with malignancies of liver, brain, breast, prostate, cervical, ovarian, and other cancers." (PMID 26404213, 2015).
cancer (continued). "Degradation of extracellular matrix and vascular basement membrane is required for invasion and metastasis of cancer, and MMP9 and MMP2 are critical proteinases that have such a role." (PMID 25811800, 2015). "FAK also induces the expression of MMP2 and MMP9 accounting for cancer invasion and metastasis via ERK or JNK pathways 31,52,53." (PMID 25351103, 2015). "Enhanced MMP-2 and MMP-9 activity has been found to contribute to cancer cell migration and invasion." (PMID 26252009, 2015). "Next, we detected the expression levels of MMP-2 and MMP-9, which are regulated by FAK and are critical for cancer cell invasion." (PMID 25689564, 2015). "FAK plays a pivotal role in the regulation of MMP2 and/or MMP9, which are considered to be critical for cancer metastasis and invasion." (PMID 26517117, 2015). "MMP-2 and MMP-9 are extracellular metalloproteinases, which play an important role in the degradation of extracellular matrix, thus facilitating cancer cell invasion and migration." (PMID 25854641, 2015). "Matrix metalloproteinase 2 (MMP-2) and MMP-9 are reported to enhance cancer cell invasion via degradation of type IV collagen." (PMID 25402510, 2015). "PEG10 has been shown to promote the expression of MMP-2 and MMP-9 in cancer cells for an enhanced invasiveness." (PMID 26680220, 2015). "Trypsin and PAR-2 activating peptide, SLIGKV, significantly increased gelatinolytic activity of MMP-2, as well as ERK/AP-1, MEK1/2, and MAPK signaling to promote cancer cell proliferation, migration, and metastasis." (PMID 26573921, 2015). "MMP-2 and MMP-9 are considered to be prognostic factors in many solid tumors, and also found to promote invasion and metastasis of malignant tumors." (PMID 26404213, 2015). "MMPs, mostly MMP2 and MMP9, are known to facilitate cancer cell invasion by degrading extracellular matrix (ECM) proteins, and are thus increased during EMT." (PMID 26450645, 2015). "Increased MMP-2 and MMP-9 activity levels are considered an important mechanism for the increased capacity of cancer cells to traverse the membrane, mimicking invasion and metastasis." (PMID 26043756, 2015). "Increasing evidence suggests that MMPs, particularly MMP-2 and MMP-9, are upregulated in cancer cells and play a critical role in these processes." (PMID 25927939, 2015). "MMP2 and MMP9 expression via the activation of NF-κB signaling promotes cancer cell migration and invasiveness." (PMID 26388610, 2015). "DATS inhibits MMP2/9 activity and the metastasis of TNBC cells, and emerges as a potential anti-cancer agent." (PMID 25927362, 2015). "MMPs, particularly MMP-2 and MMP-9, are key enzymes known to degrade the components of surrounding ECM during cancer invasion and metastasis." (PMID 25803820, 2015). "The activity of active MMP-2 was enhanced when HMF were co-cultured with MDA-MB-231, and active MMP-9 activity was enhanced when HMF were co-cultured with SUM149 or SUM159 cancer cells." (PMID 28721370, 2015). "MMP-2 and MMP-9 are two key regulators of extracellular matrix (ECM) remodeling and play a crucial role in angiogenesis, migration of cancer cells and metastasis." (PMID 25619880, 2015). "Among them, MMP-2 (gelatinase A) and MMP-9 (gelatinase B) are known to be strongly correlated with metastatic potential of cancer cells." (PMID 26180515, 2015). "Tissue inhibitor of metalloproteinase (TIMP2) is involved in the regulation of matrix metalloproteinase 2 (MMP2) and shown to implicate in cancer development and progression." (PMID 25136829, 2014). "More importantly, the MMP secretion was Notch dependent because inhibition of the Notch effector Hey1 decreased both MMP2 and MMP9, which eventually decreased cancer cell invasion." (PMID 24931473, 2014). "MMP-2, or gelatinase A, is an important MMP that is increased in several cancers, and in PCa in particular." (PMID 24798191, 2014). "MMP2 and MMP9 play important roles for cancer metastasis, and IL-17A can affect the expression of MMP2 and MMP9." (PMID 25250801, 2014).
cancer (continued). "Among the MMP family members, MMP-2 and MMP-9 are molecules important for cancer invasion, and have been shown to be highly expressed in cancer cells." (PMID 25202430, 2014). "Tight junction molecules, such as CLDN1, improved invasion activity in cancer cell lines through activation of MT1-MMP-1 and MMP-2, and peak expression of claudin-4 RNA has been temporally associated with the implantation window in humans." (PMID 24564230, 2014). "rVP1 inhibits cancer cell migration/invasion by downregulating integrin/FAK/Akt/GSK-3β signaling and MMP-2 activity." (PMID 25004182, 2014). "With regard to MMP-2 and MMP-9, it is well known that these enzymes promote cancer progression through extracellular matrix and basement membrane degradation, resulting in the exposure of cryptic locations linked to invasion, metastasis and angiogenesis." (PMID 25432084, 2014). "Mechanistically, we demonstrated that the anti-cancer activity of NTP involves cytoskeletal rearrangements, resulting in changes in cellular morphology, as well as inhibition of the MMP-2/-9/uPA system and Akt/ERK signalings." (PMID 24667444, 2014). "PIAS1 suppresses TGFβ-dependent activation of the matrix metalloproteinase MMP2 and the invasiveness of breast MDA-MB-231 cancer cells." (PMID 25594015, 2014). "Most published data on MMP-2 and MMP-9 address the role of these proteins in encouraging the aggressiveness of cancers." (PMID 25097794, 2014). "Namely, neutrophils found in the early phase of cancer cell dissemination expressed CCR1 exclusively and MMP9 preferentially, whereas fibrocytes accumulated in later phase expressed MMP2 exclusively." (PMID 25326065, 2014). "TFN1, CD44, and MMP2 are all EMT markers genes, whose aberrant expressions were involved in the EMT of cancer." (PMID 24402783, 2014). "TIMP2 possesses a complex role in cancer through its ability to regulate MMP activity and to inhibit especially MMP2." (PMID 25136829, 2014). "Down-regulated genes such as MMP2, MAPK1, TBFRS7, REL A, SAFB, FES identified GO terms listed as TGF-beta signaling, angiogenesis, IL-4 signaling, cartilage development and cancer-related pathways." (PMID 24756038, 2014). "In the present paper, the tissue expression of MMP-2 and TIMP-2 was observed in cancer and interstitial inflammatory infiltrate cells as well as in normal colorectal epithelium." (PMID 24395652, 2014). "SATB1 is a global chromatin organizer that directly regulates the expression of ERRB2, MMP2, ABL1 and E-cadherin to act as a key regulator of cancer development." (PMID 24675979, 2014). "The serum levels of MMP-2 and TIMP-2 in cancer patients were significantly lower than those in control group, but the percentage of positive immunoreactivity of these proteins were higher in malignant and inflammatory cells as compared to normal tissue." (PMID 24395652, 2014). "Previous research has demonstrated that up-regulation of FOXM1 increased the expression of MMP-2, MMP-9 and VEGF-A, resulting in the promotion of proliferation, migration and invasion of cancer cells." (PMID 24885308, 2014). "Western blotting study shows that downregulation of Btbd7 in NCI-H1299 cells significantly upregulated E-cadherin expression and downregulated snail 2 (slug), MMP2 and MMP7 expression in cancer cells." (PMID 25253020, 2014). "Numerous clinical and experimental studies have demonstrated an increase in particular MMPs, especially MMP-2 and MMP-9 with cancer progression." (PMID 25299052, 2014). "MMP-2 and MMP-9 are zinc-dependent endopeptidases that play critical roles in cancer progression and metastasis." (PMID 24581171, 2014). "The metalloproteinases MMP-2 and MMP-9 are involved in the regulation of cancer cell migration and metastasis, while the transcription factor EGR-1 participates in the regulation of cell proliferation, migration and apoptosis." (PMID 25260978, 2014).
cancer (continued). "The decrease in MMP-9 secretion following treatment with siRNA anti-Rac3 can also be involved in its inhibitory effect on VM in MDA-MB-231 cells, as it was described that both MMP-2 and MMP-9 play an important role in VM in cancers." (PMID 23388133, 2013). "In human cancer cells, MMP-1, MMP-2, MMP-3, MMP-9, and MMP-13 have been found to be correlated with malignant grade and metastasis." (PMID 24047437, 2013). "The evidence for MMPs, including MMP-2 and MMP-9, as active contributors to cancer progression arises from animal studies." (PMID 24137425, 2013). "Before the operation, the highest mean concentration of MMP-2 was found in patients with unresectable cancer, whereas the highest level of MMP-9 was in patients with resectable cancer." (PMID 23768069, 2013). "Among these MMPs, MMP2 and MMP9 are abundantly expressed, secreted, and activated in various malignant tumors." (PMID 24138815, 2013). "To determine the MMP profile in astrocyte CM, we performed gelatin zymography for MMP-2 and MMP-9, well known to correlate with the invasive and metastatic potentials of various cancers." (PMID 24324647, 2013). "Gelatinases A (MMP-2) and B (MMP-9) digest gelatins or denatured collagens and are two of the most widely studied MMPs in cancer." (PMID 23696797, 2013). "Altered expression of Twist, matrix metalloproteinase (MMP)-2 and MMP-9 proteins has been identified in various types of human cancers." (PMID 23935727, 2013). "Previous studies on cancer cells showed that CSE1L was colocalized with MMP-2 in cytoplasmic areas near the cell membranes and invadopodia, and that CSE1L overexpression enhanced MMP-2 secretion and the invasive ability of cancer cells." (PMID 23369209, 2013). "Specifically our model will focus on two distinct types of MMP, i.e., soluble, diffusible MMPs (e.g., MMP-2), and membrane-bound MMPs (e.g., MT1-MMP), and the roles each of these plays in cancer invasion." (PMID 23565505, 2013). "Downstream from MAPK signaling, JNK activation helps regulate cancer cell invasion and expression of MMP-1, MMP-2, and MMP-9." (PMID 23878609, 2013). "Since HAG up-regulates miR-29b expression and down-regulates the ECM degrading enzyme MMP-2 gene expression, we further investigated the functional effect of HAG on cancer cell migration." (PMID 24130681, 2013). "MMP-2 and MMP-9 are the key enzymes for type IV collagen degradation and are considered to be important for cancer invasion." (PMID 23878609, 2013). "Significantly increased mRNA expression of MMP-2 and MMP-9 and decreased expression of TIMP-1 and TIMP-2 was observed in the cancer-induced group." (PMID 23599733, 2013). "Bmal1 knockdown-induced cancer cell invasion was accompanied by activation of the PI3K-Akt-MMP-2 pathway, and was prevented by inhibitors of PI3K, Akt or MMP-2." (PMID 23563360, 2013). "Consistent with this prediction, increased expression of the cancer invasion-related genes matrix metalloproteinase (MMP)-1, MMP-2, epidermal growth factor receptor (EGFR) and cyclooxygenase 2 (COX-2) were detected in the CD44+ stem-like cells." (PMID 23833643, 2013). "The results suggest that the anti-invasive action of tas1611 is partly mediated by diminishing the ability of cancer cells to degrade the components of the ECM by modulating the expression and activity of MMP-2 and MMP-9." (PMID 24137425, 2013). "MMP2 is a key member of the matrix metalloproteinase (MMP) family, which is involved in many pathological conditions, particularly cancer metastasis and angiogenesis." (PMID 24083576, 2013). "Among these enzymes, MMP-2 and MMP-9 can degrade most ECM components and are profoundly involved in the development of cancer invasion and metastasis." (PMID 24053256, 2013). "The roles of MMP-2, MMP-9, ICAM-1, and VEGF in invasion, adhesion, and angiogenesis of cancer are well known and regulated by NF-κB." (PMID 23864892, 2013).